SLC12A1 (solute carrier family 12 member 1)
Diseases named in the same sentence as SLC12A1 in open-access papers:
SLC12A1 is named in the same sentence as 95 diseases in open-access papers, as found by Europe PMC text mining. Sharing a sentence is not in itself a finding about the gene and the disease. The quoted sentences say what the papers report.
Bartter syndrome (55 papers, 2011 to 2026). "One patient was diagnosed with MODY5, caused by a known mutation in the HNF1B gene, and one patient was diagnosed with Bartter syndrome type 1, resulting from a known mutation in the SLC12A1 gene." (PMID 41828581, 2026). "Type I Bartter syndrome is a rare autosomal recessive tubulopathy resulting from mutations in the SLC12A1 gene, leading to defective sodium-chloride reabsorption in the thick ascending limb of the loop of Henle." (PMID 41883686, 2026). "Five different types of Bartter syndrome have been identified due to inactivating mutations in SLC12A1, KCNJ1, CLCNKB, BSND, or CASR." (PMID 39405114, 2024). "Bartter syndrome is classified into five major genotypes caused by mutations in different genes, namely SLC12A1, KCNJ1, CLCNKB, CLCNKA, BSND, and MAGED2." (PMID 38238844, 2024). "Loss of function mutations in SLC12A1 or KCNJ1 in humans causes Bartter syndrome, which is characterized by hypokalemia, metabolic alkalosis (body pH elevation), polyuria (excess urination), salt wasting, hypercalciuria, and hypotension." (PMID 38195585, 2024). "Bartter syndrome type 1 is caused by mutations in the solute carrier family 12 member 1 (SLC12A1), encoding the sodium-potassium-chloride cotransporter-2 (NKCC2)." (PMID 37908481, 2023). "Bartter syndrome is caused by mutations in SLC12A1 encoding NKCC2 (type I), KCNJ1 encoding ROMK (type II), CLCNKB encoding ClC‐Kb (type III) or BSDN encoding Barttin (type IV) (OMIM: 601678, 241200, 607364 and 602522, respectively)." (PMID 32603001, 2021). "Slc12a1 encodes a renal-specific Na-K-2Cl cotransporter, and loss-of-function mutations in this gene are related to Bartter’s syndrome, an autosomal recessive form of metabolic alkalosis." (PMID 32168507, 2020). "In patients suffering from type I Bartter syndrome (antenatal Bartter’s disease, hyperprostaglandin E syndrome), compound heterozygous or homozygous mutations of the SLC12A1 gene (OMIM 601678) were identified as cause." (PMID 25084970, 2014). "To date, more than 70 causative mutations of SLC12A1 were found in patients showing lead symptoms of antenatal Bartter syndrome, Bartter syndrome, and/or reduced blood pressure." (PMID 25084970, 2014). "Bartter syndrome was suspected based on the biochemical profile, perinatal history, and persistent electrolyte imbalance, and subsequently confirmed by identifying a pathogenic SLC12A1 variant (NM_001184832:c.1327G>A)." (PMID 41883686, 2026). "BS type 1 represents 11% of the cohort (3 of 27): patients SOR0079, SOR0082 and SOR0098 carried two pathogenic or likely pathogenic variants in compound heterozygosity in the SLC12A1 gene, thus satisfying criteria for a conclusive diagnosis of Bartter syndrome type 1." (PMID 37537162, 2023). "Whole-exome sequencing (WES) excluded pathogenic variants in renal tubulopathy genes including SLC12A3 (Gitelman syndrome), SLC12A1, CLCNKB, BSND, KCNJ1, MAGED2 (Bartter syndrome), and CASR, CLCNKA, KCNJ10 (hypokalemia-associated genes)." (PMID 40893942, 2025). "Bartter syndrome, encompassing types 1–3, stems from mutations in genes such as NKCC2 (SLC12A1), ROMK (KCNJ1), or CIC-Kb (CLCNKB), culminating in hypokalemic alkalosis and hypercalciuria." (PMID 40126616, 2025). "Other syndromic variants of AI, particularly those involving mutations in SLC12A1 or KCNJ1, may present clinical features similar to Bartter syndrome and can progress more rapidly toward ESRD." (PMID 41427162, 2025). "We identified two likely pathogenic nonsense variants in compound heterozygous state (p.[(Gln75*)];[Arg761*]) in the SLC12A1 gene (Na-K-2Cl cotransporter NKCC2, pathogenic mutations cause type I BS (OMIM #601678)) confirming a clinical diagnosed of neonatal Bartter syndrome type 1." (PMID 32997713, 2020). "Production of pathologic proteins regulated by defective genes in exosomes from certain genetic renal diseases may be either decreased (PKD1 in ADPKD) or totally absent (SLC12A1 in Bartter syndrome type 1)." (PMID 32849923, 2020).
Hypertension (52 papers, 2009 to 2025). The presence of chronic increased pressure in the systemic arterial system. "Mutations of SLC12A1 were observed having strong association to blood pressure and hypertension in the general population." (PMID 36305246, 2022). "Recently, rare heterozygous missense mutations of SLC12A1 were identified in a screen of members of the Framingham Heart Study to act beneficially against the risk of arterial hypertension and death due to cardiovascular disease." (PMID 25084970, 2014). "Carriers of single heterozygous pathogenic variants in SLC12A1, SLC12A3, and KCNJ1 were shown to have a reduced prevalence of hypertension and for SLC12A3 also in lower serum potassium levels." (PMID 37612755, 2023). "Recently, SLC12A1 has been strongly suggested as a candidate gene for hypertension in a large-scale meta-analysis." (PMID 32822870, 2020).
Hypokalemia (11 papers, 2012 to 2025). An abnormally decreased potassium concentration in the blood. "We report a now 7-year-old Japanese girl with polyuria, hyponatremia, hypokalemia, and metabolic alkalosis, in whom compound heterozygous novel SLC12A1 mutations were identified." (PMID 37908481, 2023). "Furthermore, the lack of association between GHD and antenatal BS, which is caused by mutations in either the SLC12A1 (type I BS) or KCNJ1 (type II BS) gene, can be explained by the observation that the correction of hypokalemia is generally easier in antenatal BS than in classic BS." (PMID 24377430, 2013).
Hypercalciuria (9 papers, 2015 to 2025). "In addition to causing renal salt-losing tubulopathy, SLC12A1 mutations are known to cause nephrocalcinosis due to hypercalciuria, as well as failure to thrive associated with abnormal calcium and phosphorus homeostasis." (PMID 37908481, 2023).
Gitelman syndrome (6 papers, 2017 to 2025). Gitelman syndrome (GS), also referred to as familial hypokalemia-hypomagnesemia, is characterized by hypokalemic metabolic alkalosis in combination with significant hypomagnesemia and low urinary calcium excretion. "Loss-of-function mutations in SLC12A3, SLC12A1, and KCNJ1 genes, essential for normal renal NaCl reabsorption, cause Bartter’s and Gitelman’s syndromes." (PMID 29495593, 2018).
Polyuria (4 papers, 2018 to 2025). An increased rate of urine production. "Further, SLC12A1, a critical regulator of sodium reabsorption and blood pressure, was downregulated and is associated with the onset of polyuria and hydronephrosis." (PMID 40863220, 2025). "Loss-of-function mutations in SLC12A1 in humans and Slc12a1 knockout in mice lead to Bartter syndrome type I, and decreased levels of Umod are likely responsible for the polyuria observed in Umod knockout mice." (PMID 29553830, 2018).
breast carcinoma (3 papers, 2016 to 2025). "Our results suggest a potential link between SLC12A1 gene expression and GLUR4 protein levels with chemoresistance in luminal breast cancer." (PMID 38003293, 2023).
cyst (3 papers, 2021 to 2024). A sac-like closed membranous structure that may be empty or contain fluid or amorphous material. "IHC staining for specific markers on serial sections of cysts showed a positive staining for both CD10 and SLC12A1 in a same cyst wall, suggesting PT and LOH origins, respectively." (PMID 34815804, 2021). "We studied the cell origin of cyst epithelial cells by conducting differential gene expression analysis and established genetic markers (LRP2, SLC12A1, CDH16, and KRT17) 21, 22 of renal tubules and CD in the epithelial cell populations, respectively." (PMID 34815804, 2021). "We validated the clustering outcomes by using specific antibodies for different nephron segments, including LRP2, SLC12A1, CDH16, KRT17 and two classical markers CD10 and AQP2(the marker of PT and CD, respectively) for IHC staining of cyst epithelial cells." (PMID 34815804, 2021).
Nephropathy (3 papers, 2014 to 2024). A nonspecific term referring to disease or damage of the kidneys. "Type I Bartter syndrome is a recessive human nephropathy caused by loss-of-function mutations in the SLC12A1 gene coding for the Na+-K+-2Cl− cotransporter NKCC2." (PMID 25084970, 2014). "In humans, nephropathy-causing reduced ion transport capacity of the NKCC2 dimers occurs if both alleles are mutated, and the recessive character of Slc12a1 mutations to cause renal disease has been shown in knockout mice as well as in our previous publication of line Slc12a1I299F." (PMID 25084970, 2014).
Andermann syndromes (2 papers, 2021 to 2024). "The SLC12 family is a nine-member gene family with three established associated human diseases: SLC12A1 (MIM No. 600839), SLC12A3 (MIM No. 600968), and SLC12A6 (MIM No. 604878), which cause Bartter, Gitelman, and Andermann syndromes, respectively." (PMID 34226616, 2021).
epilepsy (2 papers, 2020 to 2025). A brain disorder characterized by episodes of abnormally increased neuronal discharge resulting in transient episodes of sensory or motor neurological dysfunction, or psychic dysfunction. "Other genes with polymorphisms validated in the GASH/Sal, namely Tsen54, Hesx1 and SLC12a1, are also related to epilepsy, albeit secondarily because polymorphisms in these genes are primarily associated with other diseases." (PMID 32168507, 2020). "Based on the patient’s clinical manifestations, previously reported disease - related genes, and our comprehensive RNA - seq data, we tentatively speculate that CLCNKB and SLC12A1 may functionally coordinate in the pathophysiological context of epilepsy." (PMID 40600194, 2025).
nephrocalcinosis (2 papers, 2023 to 2025). Nephrocalcinosis is a disorder that occurs when too much calcium is deposited in the kidneys. "Type I results from a mutation in the SLC12A1 gene in the neonatal population with polyhydramnios, nephrocalcinosis, hypokalemic alkalosis, and hyposthenuria." (PMID 40666068, 2025).
renal carcinoma (2 papers, 2020 to 2024). A carcinoma arising from the epithelium of the renal parenchyma or the renal pelvis. "Additionally, the expression of SLC12A1 is strongly correlated with patient survival duration in renal carcinoma." (PMID 39348357, 2024). "Many studies have shown that SLC12A1, ATP1A1, and PDHA1 are low-expressed in renal cancer and play an important role in the development of tumors." (PMID 32699530, 2020). "In this study, we analyzed the databases of GEO, TCGA, GEPIA, Oncomine, and found that six genes (SUCLG1, PCK2, GLDC, SLC12A1, ATP1A1, and PDHA1), are related to the survival prognosis of patients with renal cancer." (PMID 32699530, 2020). "It has been reported that Solute carrier family 12 member 1 (SLC12A1), Sodium/potassium-transporting ATPase subunit alpha-1 (ATP1A1) and Pyruvate dehydrogenase E1 component subunit alpha (PDHA1) are differentially expressed in renal cancer tissues." (PMID 32699530, 2020).
colorectal adenoma (1 paper, 2023). An adenoma that arises from the colon or rectum. "We studied the relationship between calcium reabsorption genes SLC12A1, KCNJ1 and SLC8A1 and colorectal adenomas." (PMID 37074453, 2023).
colorectal cancer (1 paper, 2016). A primary or metastatic malignant neoplasm that affects the colon or rectum. "Other candidates, PARG and TDGF1, have been associated with cancer regulation; however, the functional role of the candidates HORMAD1, PIGC, NCAM2, INO80D, SLCO2A1, SLC12A1, and METTL19 was unclear in colorectal cancer." (PMID 27383761, 2016).
diabetic nephropathy (1 paper, 2014). "Indeed, in our previous study, the expression levels of SLC12A1 and UMOD were significantly different between diabetic nephropathy patients and healthy volunteers (presented in American Society of Nephrology in November 2012)." (PMID 25275511, 2014).
gallstones (1 paper, 2025). Solid crystalline precipitates in the biliary tract, usually formed in the gallbladder, resulting in the condition of cholelithiasis. "New missense and nonsense mutations in both SLC12A1 and KCNJ1 genes associated with the risk of gallstone formation at an early age have been identified." (PMID 40149408, 2025).
Glucose intolerance (1 paper, 2022). Glucose intolerance (GI) can be defined as dysglycemia that comprises both prediabetes and diabetes. "Inhibition of Cl−loaders such as Nkcc1 (Slc12a2) and others (Nkcc2, Slc12a1) with loop-diuretics bumetanide or furosemide impaired islet insulin secretion in vitro and resulted in glucose intolerance in different mouse models." (PMID 36580474, 2022).
hearing loss (1 paper, 2022). "All of these demonstrate that SLC12A1 has a role in hearing loss, but it is probably through polygenic or multifactorial ways." (PMID 35154281, 2022). "Except the known deafness gene SLC12A2 discussed earlier, disrupted SLC12A1 was also reported to be involved in hearing loss." (PMID 35154281, 2022). "In that case, translocation of the SLC12A1 and ATE1 (arginyltransferase 1) genes was found in a boy with nonsyndromic hearing loss; however, no hearing impairment occurred in his brother, father, and grandfather who have the same translocation." (PMID 35154281, 2022).
heart failure (1 paper, 2023). Inability of the heart to pump blood at an adequate rate to meet tissue metabolic requirements. "For example, prototypical loop diuretics, such as furosemide, bumetanide, and torsemide, can bind to chloride cotransporters (NKCCs: SLC12A1) and block ion transport directly and can, therefore, be used to treat heart failure, liver scarring, or kidney disease." (PMID 36787192, 2023).
hyperparathyroidism (1 paper, 2021). Hyperfunction of the parathyroid glands resulting in the overproduction of parathyroid hormone. "Recent studies suggested that SLC12A1 (NKCC2) could be involved in the pathogenesis of hyperparathyroidism." (PMID 34768847, 2021).
kidney cancer (1 paper, 2020). Primary or metastatic malignant neoplasm involving the kidney. "Kidney cancer patient with SUCLG1, GLDC, SLC12A1, PCK2, ATP1A1 and PDHA1 alteration showed highest mortality." (PMID 32699530, 2020).
liver cancer (1 paper, 2016). An epithelial or non-epithelial malignant neoplasm that arises from the liver. "Together, these results indicate that SLC12A1 is consistently upregulated in a small group of liver cancer patients and suggest that SLC12A1 might function as an oncogene in HCC." (PMID 27447551, 2016). "Top median-ranked gene SLC12A1, a member of the Na+-dependent subgroup of solute carriers, was overexpressed in 5%~25% of the samples we analyzed, suggesting it might be involved in HCC pathogenesis in a subset of liver cancer patients." (PMID 27447551, 2016).
migraine with aura (1 paper, 2025). A migraine disorder characterized by episodes that are preceded by focal neurological symptoms. "Similarly, the shared target SLC12A1 of both Diuretics and Agents acting on the renin‐angiotensin system is also connected to a decreased risk of migraine with aura (OR (95% CI) = 0.954 (0.927−0.981) and PSMR = 1.08×10−3)." (PMID 41261954, 2025). "SMR and INTACT confirmed the validity of BLM, C12orf76, GPATCH4, PAM, SERPINC1 for migraine, and ALMS1, GPATCH4, NCF2, SLC12A1, ZKSCAN8P1 for migraine with aura." (PMID 41261954, 2025). "The results of the SMR, colocalization, and INTACT sensitivity analyses provided further validation of BLM, C12orf76, GPATCH4, PAM, SERPINC1 as contraindicated drugs’ target genes for migraine, and ALMS1, GPATCH4, NCF2, SLC12A1, ZKSCAN8P1 for migraine with aura." (PMID 41261954, 2025).
ovarian carcinoma (1 paper, 2016). A malignant neoplasm originating from the surface ovarian epithelium. "A pathogenic role in cancer was further reported in ovarian cancer cell lines, which exhibited increased SLC12A1 expression levels." (PMID 26831905, 2016).
partial albinism (1 paper, 2022). "For example, SLC24A5, MYEF2, and CTXN2 gene variations have been associated with differences in skin pigmentation, partial albinism, and retinal pigment; SLC12A1 plays a key role in concentrating urine, and its defects result in some Bartter-like syndromes." (PMID 35440892, 2022).
kidney disease (15 papers, 2014 to 2025). "Indeed, loss of function mutations in SLC12A1 can cause Bartter I syndrome, a rare genetic kidney disease marked by severe natriuresis with normal or low blood pressure, hypercalciuria, hyperparathyroidism, hypokalemia, and metabolic alkalosis." (PMID 33672238, 2021). "Genes downregulated by EGCG, especially SLC12A1 or LOX, can be associated with several processes related to renal disease, most significantly “abnormal renal water reabsorption”." (PMID 37627594, 2023). "This might reflect a decreased activity of the mutant SLC12A1 in the gastrointestinal tract and/or pancreatic beta cells and/or might be a secondary effect of the kidney disease." (PMID 25084970, 2014).
cancer (8 papers, 2016 to 2025). A tumor composed of atypical neoplastic, often pleomorphic cells that invade other tissues. "Differences between Non-Cancer (NC, n = 36) and PCa (n = 40) were only significant for SLC12A1 in EVs (median levels ~50-fold higher in the PCa EV samples, FDR p = 0.034; edgeR)." (PMID 36765747, 2023). "WNK proteins have also been reported to promote cancer cell proliferation; therefore, we checked the phosphorylation status of WNKs under SLC12A1 knock-down conditions." (PMID 27447551, 2016).
tumor (6 papers, 2015 to 2025). "Until recently, the role of SLC12A1 in tumor metabolism has been poorly understood, warranting further investigation into its coordination of tumorigenesis in PM." (PMID 40707702, 2025). "SLC12A1 was closely related to the low degree of immune infiltration of the two crucial immune cells and it was silenced in tumor tissues." (PMID 35135552, 2022). "Consistent with in vitro results, treatment with the SLC12A1 antagonist Bumetanide delayed tumor formation and reduced Hep3B cell tumor size in mouse xenografts." (PMID 27447551, 2016). "Using ccRCC and matched normal kidney samples, it was also evidenced that the increased levels of miR-185 and miR-21 in tumors correlate with the loss of function of specific tumor suppressors such as PTPN13, SLC12A1 and TCF21." (PMID 26670229, 2015). "We then applied immunohistochemical analysis to detect SLC12A1 in tumors of xenograft models to test whether SLC12A1 was continuously expressed during tumor formation." (PMID 27447551, 2016). "The results showed that SLC12A1 expression was the same in normal and tumor groups." (PMID 27447551, 2016). "Similarly, SLC12A1 is regulated by NFIC, GATA2 and FOXC1, ensures ionic balance and cellular volume, thereby supporting tumor cell survival and aggressive behavior." (PMID 39348357, 2024).
SLC12A1 also shares sentences with these, for which no sentence is quoted: diabetes (5 papers); diabetes insipidus (3); Hyperkalemia (3); infection (3); nephrogenic diabetes insipidus (3); Ureteral obstruction (3); acute kidney injury (2); Alkalosis (2); colitis (2); genetic disorder (2); Gordon syndrome (2); hydronephrosis (2); hyperuricemia (2); Hypocalciuria (2); Insulin resistance (2); iron deficiency (2); nephrotic syndrome (2); Obesity (2); renal tubular disease (2); Wilson disease (2); acute tubular necrosis (1); Ascites (1); cerebral infarction (1); Cerebral ischemia (1); chronic kidney disease (1); Cirrhosis (1); congestive heart failure (1); cystic kidneys (1); Dent disease (1); depression (1).
A further 36 diseases each share a sentence with SLC12A1 in 1 paper.